HMGA2 (high mobility group AT-hook 2)
Diseases named in the same sentence as HMGA2 in open-access papers (continued):
Sharing a sentence is not in itself a finding about the gene and the disease.
tumor (continued). "The let-7 family functions as a well-known tumor suppressor and targets the oncogenes rat sarcoma (RAS) and high mobility group AT-hook 2 (HMGA2)." (PMID 23860207, 2013). "In this study, we have established the suppression of cell proliferation in cultured RB cells of differing tumor aggressiveness (Y79 and WERI Rb1) using the HMGA2 gene-silencing technique." (PMID 23077401, 2012). "Let-7a target genes relevant to transformation and subsequent tumor development include RAS, MYC, IGF2BP1 and HMGA2." (PMID 21853155, 2011). "In general, let-7 miRNAs act as a tumor suppressor by targeting oncogenes such as RAS and HMGA2 and let-7 miRNAs are downregulated in many cancers from solid organs." (PMID 20949044, 2010). "Since let-7 miRNAs generally play a tumor-suppressive role as targeting oncogenes such as RAS and HMGA2, our results suggest that AZ-P7a cells release let-7 miRNAs via exosomes into the extracellular environment to maintain their oncogenesis." (PMID 20949044, 2010). "Recent studies have shown that let-7 plays a role as tumour suppressors by negatively regulating expression of RAS and HMGA2 oncogenes." (PMID 19156147, 2009). "Regarding biological functions, let-7f inhibits tumor cell proliferation, invasion, metastasis, stemness maintenance, and metabolic reprogramming by targeting multiple oncogenes (e.g., MYH9, HMGA2, ADAMTS1, Periostin) and key signaling pathways (e.g., MAPK, Wnt, PI3K/AKT)." (PMID 42293764, 2026). "HMGA2, a chromatin remodeling protein, is known to promote cellular plasticity and stemness, potentially synergizing with LEF1-driven WNT activation to enhance tumor aggressiveness." (PMID 39851951, 2025). "Next, transcription factor analysis using the SCENIC pipeline revealed that HMGA2, a key transcription factor known to regulate LAMC2 expression in tumors, was significantly activated in Tum_1 cells, suggesting a role in promoting tumor basal stem‐like cell activity." (PMID 40470730, 2025). "This consistent increase suggests that Hmga2 may serve as a crucial molecular target in TPA- and mezerein-induced tumour progression in Bhas42 cells." (PMID 40182023, 2025). "Thus, we discovered the moonlighting function of 6PGD in promoting tumor growth and migration via CCNA2 and HMGA2, respectively." (PMID 40611205, 2025). "Notably, dual targeting strategies demonstrate promise: HMGA2 depletion sensitizes tumors to chemotherapy, while combining HMGA2/CD47 blockade synergistically enhances anti-tumor efficacy." (PMID 40703517, 2025). "KY tumor organoids had a higher percentage of SPC-high cells compared to KPY tumor organoids and do not exhibit the evidence of Hmga2-high Group 4 cell state." (PMID 39930268, 2025). "The HMGA2 mRNA expression in tumor and non-tumor tissue was below the level of reliable evaluation of expression pattern, which is in line with IHC negative results." (PMID 37466765, 2024). "HMGA2 assumes the capacity to mediate transforming growth factor-beta (TGF-β) signaling, thereby exerting regulatory influence over crucial processes encompassing epithelial differentiation, tumor invasion, and metastasis." (PMID 39591457, 2024). "The majority of research has shown that the miRNA/HMGA2 axis has important roles in tumor progression; however, there has been a lack of investigation into the role of miRNA/HMGA2 signaling in chemotherapeutic resistance of BC." (PMID 38753081, 2024). "Indeed, let-7 inhibits LC tumor growth by targeting c-MYC, KRAS and HMGA2, binds to DICER, i.e., a RNAase which processes miRNAs, and induces cell autophagy in LC." (PMID 38245882, 2024). "This suggests that HMGA2 may interact with IGF2BP2 to facilitate the expression of key oncogenes in HCC, contributing to tumor growth and progression." (PMID 39591457, 2024). "Moreover, PiHL knockdown reduced HMGA2 levels and restored sensitivity to Oxaliplatin treatment in a CRC xenograft model, thus linking HMGA2 tumor levels to Oxaliplatin resistance in CRC." (PMID 36980621, 2023).
tumor (continued). "Furthermore, the tumor suppressing function of miR-107 has been previously reported in HCC via targeting oncogenic genes, including RGS4, HMGA2, HMGCS2, cofilin-1, and Wnt/β-catenin." (PMID 37744274, 2023). "Subsequently, it has been shown that HMGA2 regulates the expression of EMT transcription factors by binding to the abundant specific AT sequences in DNA and changing the conformation of chromatin, thereby enhancing tumor aggressiveness." (PMID 38304037, 2023). "Importantly, we also identified a Basal TF network, including ZBED2, KLF7, HMGA2, and NR3C1 as major regulators, whose expression was restricted to the basal component of tumours, according to scRNA-seq data." (PMID 36944729, 2023). "Our analyses suggest that there are mainly two distinct cell states that exist in the tumor organoids: an SPC-high state resembling AT2 cells and lung lineage specifiers (Group 1 and Group 2) and an Hmga2-high state with similarity to known oncogenic signaling pathways (Group 3 and Group 4)." (PMID 36993454, 2023). "Similarly, our results also confirmed that depletion of Hmga2 suppressed the expression and secretion of CCL2 in the CT26 subcutaneous tumor model by qPCR and ELISA assays." (PMID 34976223, 2022). "We revealed that exosomal HMGA2 protein from EBV-positive NPC cells can be delivered into endothelial cells, attenuate endothelial junction integrity, increase EndMT, and consequently promote tumor metastasis." (PMID 35388172, 2022). "Unsupervised clustering on the expression profiles issued from this series suggested two distinct subgroups: one composed of various molecular subtypes including CSF1 and FN1 rearranged samples and one composed of four tumors harboring an HMGA2::NCOR2 fusion, suggesting distinct tumor entities." (PMID 36439507, 2022). "While we did not observe an association between response to bintrafusp alfa and PD-L1 expression on tumor cells and cells in the TME, RNAseq analysis of tumor samples from patients with TNBC identified high expression of the HMGA2 gene to be a potential biomarker of response to bintrafusp alfa." (PMID 36568239, 2022). "Tumor samples from 4 patients who experienced disease control (2 PRs and 2 SDs by IRC assessment) with bintrafusp alfa had a median 32-fold higher expression of HMGA2 (q=4.34e-14 as computed by DESeq2) than samples from patients who had PD." (PMID 36568239, 2022). "Taken together, these results suggest that HMGA2 may inhibit the xenograft tumor proliferation and growth through the regulation of EMT-related gene expressions in the xenograft RCC tumor model." (PMID 35439951, 2022). "However, the expression level of target genes, including HMGA2 and FZD3, in tumor tissues was overexpressed in comparison to the normal tissues (p < 0.01)." (PMID 35488374, 2022). "The tumor size reduction in the cotreatment group did not involve HMGA2 downregulation in the tumors, as epigenetic repression of DOT1L target genes would require continuous exposure to EPZ5676 as previously demonstrated." (PMID 34887387, 2021). "However, other studies report that miR-150-5p inhibits Wnt-β-catenin signaling via targeting GSKIP and HMGA2, or suppresses MMP14, or GLUT1 to exert its tumor-suppressive properties in NSCLC." (PMID 34193018, 2021). "This increased let-7 expression in differentiated tumor cells (or non-TICs) inhibits the expression of H-Ras and HMGA2, known let-7 target genes that promote tumor self-renewal and proliferative capacity." (PMID 34572067, 2021). "The average tumor grade was also increased, with c-Junfl/fl; lsl-K-RasG12D animals exhibiting grade 4 LADCs, which were HMGA2+/TTF-1– and not observed in controls, and some additionally showing lepidic predominant adenocarcinoma (formerly BAC) lesions." (PMID 34236045, 2021).
tumor (continued). "In addition, there is some evidence to show that, during DNA damage, HMGA2 expression induces and subsequently sustains ATR and CHK1 levels, which prolongs G2/M arrest and enhances tumor cell survival in different human tumors with high HMGA2 expression." (PMID 33668453, 2021). "Analysis of let-7a common targets, RAS and HMGA2, revealed no impact of let-7a, suggesting tumor growth suppression occurred through a different pathway." (PMID 32102476, 2020). "In vitro and in vivo experiments demonstrated that let-7a overexpression could inhibit cell proliferation and tumor growth of LSCC and simultaneously down-regulate the expression of HMGA2." (PMID 32432318, 2020). "Interestingly, miR-491 was recently reported to act as a tumor-suppressive microRNA by inhibiting the known IGF2BP targets IGF2 and HMGA2." (PMID 32545414, 2020). "In some neoplasia, however, disease severity does not always correlate with increased HMGA2 expression levels, necessitating the resolution of other biomarkers in the HMGA2 pathway." (PMID 32365712, 2020). "HMGA2 and IGFBP1 have been shown to antagonize the tumor-suppressive activity of let-746." (PMID 32651364, 2020). "As compared with the NC inhibitor group, tumour growth was inhibited (P < .05) in the si‐HMGA2 group, whereas the let‐7g‐5p inhibitor + si‐HMGA2 group did not display any notable difference (P > .05)." (PMID 32000296, 2020). "However, in most of the LM tumor samples, and in normal tissue adjacent to IVL, expression levels of HMGA2 were less than 1% of the expression in the IVL tumors." (PMID 32372565, 2020). "On the other hand, in most uterine leiomyomata, these chromosomal breakpoints mostly occur 10–100 kilobases upstream of the HMGA2 coding region such that full-length gene transcripts are expressed in these tumor types with or without chimeric forms." (PMID 32365712, 2020). "Moreover, studies have also reported that oxidative stress, which is an important aspect of tumor microenvironment, downregulates miR-20b-5p and E2F1 via overexpression of HMGA2." (PMID 32752229, 2020). "We have shown that the WNT10B/β-catenin/HMGA2/EZH2 signaling axis is critically important in chemo-resistant TNBC and that targeting this network can prolong survival by repressing primary tumor growth and multi-organ metastases to both the lungs and lymph nodes." (PMID 31861131, 2019). "As we have seen a 3′ rearranged form of HMGA2 in only two of 15 UCS and one of ten OCS, we hypothesize that mechanism(s) other than HMGA2-rearrangements may be active in these tumours." (PMID 31217897, 2019). "Results of IHC analyses of DDX39A, HMGA1, HMGA2, HOXC9, and PBX1 expression in tumor samples." (PMID 31188873, 2019). "HMGA2 knockdown regulates autophagy via MSI2-Beclin1 interactions to inhibit NF1 MPNST growth, revealing potential therapeutic targets for these untreatable tumours." (PMID 31053152, 2019). "On the basis of these results and considering the involvement of HMGA2 in cell migration, we tested whether HMGA2-AS1 natural antisense lncRNAs were involved in this key tumor feature." (PMID 32010621, 2019). "Given that HMGA2 and PLAG1 rearrangements have been described in other neoplasms with epithelial-myoepithelial differentiation, in particular in PAs, we sought to define whether AMEs may harbor fusion genes known to underpin PAs." (PMID 30675516, 2019). "In general, high levels of DDX39A and PBX1 were found in all tumor samples while HMGA proteins showed poor (HMGA1) or no (HMGA2) endogenous expression in tumor cells." (PMID 31188873, 2019). "Nevertheless, HMGA2 levels did not follow the increase in tumor histological grade, nor were they correlated with tumor size." (PMID 31096664, 2019). "Interestingly, HMGA2 is re-expressed in many human malignancies, including PDAC, where high expression correlates with lymph node metastasis, increased tumour grade, and reduced patient survival." (PMID 30228296, 2018).
tumor (continued). "Some studies demonstrated that miR-154-5p could act as a tumor suppressor gene through targeting CCND2, STAG2, E2F5, HMGA2 and TLR2." (PMID 30266084, 2018). "Correlation of overall survival with HMGA1 and HMGA2 protein expression showed that PDAC patients with tumours that were both HMGA1negative and HMGA2negative had better overall survival than patients whose tumours expressed HMGA1 and/or HMGA2 (p = 0.0022)." (PMID 30228296, 2018). "To test whether Hmga1 compensates for Hmga2 in PDAC metastasis, we generated PDAC cell lines from tumours from KP172CT;Hmga2+/+ and KP172CT;Hmga2CK/CK mice (n = 4 each)." (PMID 30228296, 2018). "Measurement of IGF1R and HMGA2 protein levels in 15 HNSCC tumor tissues and adjacent non-tumor tissues showed significantly higher levels of both proteins in the HNSCC tumor tissues than in the non-tumor tissues." (PMID 29507664, 2018). "Additionally, the expression trend of JUB, HMGA2 and MCM2 was increased along with the tumor differentiation grades." (PMID 29596435, 2018). "All the authors agreed on reporting high levels of expression of both HMGA1 and HMGA2 in MDA-MB-231 cells, which have some properties of stem cells (self-renewal and invasion), while the property of metastasis is a specific characteristic of tumour cells." (PMID 29853899, 2018). "Positive membrane staining of IGF1R and positive nuclear staining of HMGA2 were observed in tumor tissues, with no or weak immunoreactivity of these proteins in adjacent non-tumor tissues." (PMID 29507664, 2018). "The results revealed that the overall survival rate was significantly lower in patients whose tumours showed double positive staining for HMGA2 and VM than those with negative expression for either of these factors." (PMID 28533522, 2017). "Several studies on human cancers have indicated that HMGA2 overexpression predicted poor prognosis without a significant correlation with tumor stage." (PMID 29383160, 2017). "One the other hand, we analysed the relation between HMGA2 expression and tumor stage, and we observed that HMGA2 expression did not correlate with stage in all WT subtype (p=0.9797) and in blastemal WT component (p=0.6604)." (PMID 29383160, 2017). "Other alterations were very rare as only one tumor showed HMGA2 overexpression (4%) and none displayed biallelic FH inactivation." (PMID 28592321, 2017). "Our data nevertheless lead us to suppose that also other players are involved in HMGA2 regulation, not least because although the let-7a and miR-30c levels differ but little among the various tumor histotypes, the levels of HMGA2 expression do." (PMID 28423547, 2017). "TSCC mRNA and protein expression were significantly up-regulated in tumor tissues when compared to adjacent non-tumor tissues, and the overexpression of HMGA2 was closely correlated with lymph nodes metastasis." (PMID 26818837, 2016). "Finally, we found that the NVP-AUY922-dependent mitigation of HMGA2 signaling occurred also through indirect reactivation of the tumor suppressor microRNA (miRNA), let-7a, or the inhibition of ERK-regulated HMGA2 involved in regulating the growth of CRC cells." (PMID 26893968, 2016). "Notably, HMGA2 is highly expressed in metastatic NSCLC, consistent with its role in promoting tumor metastasis." (PMID 27821801, 2016). "HMGA2 is one of the few genes found to be activated in this tumor type; however, no previous study has quantified its expression." (PMID 27835588, 2016).
tumor (continued). "91% of the EOC tissues were strongly immunoreactive for HMGA2, whereas no HMGA2 protein was detected in the normal ovarian tissue surrounding the tumor and in the Fallopian tube tissue with normal epithelium that was used as negative control." (PMID 25749380, 2015). "In order to explore any disease relevance connecting HMGA1 and HMGA2 expression and tumor phenotype, we stained CRC tumor tissue arrays for these proteins and evaluated expression in relationship to various parameters including tumor stage, histopathologic characteristics, and disease outcomes." (PMID 26244988, 2015). "Our results showing coordinate induction of HMGA2, TGF-β along with the EMT markers are consistent with the model that viral non-coding RNA targeted depletion of HNF4α sets the stage for the development of HCC, tumor invasion and metastasis." (PMID 26157476, 2015). "Copy number increase of HMGA2 and PSCA was detected in one and four tumor, respectively." (PMID 25502777, 2014). "Immunohistochemical staining showed that FHIT expression was decreased in matched lymph node metastatic tissues compared to primary tumor tissue (9 of 40 cases), but MTDH and HMGA2 were significantly activated (11 of 40 and 10/40 cases, respectively) in the matched lymph nodes." (PMID 25340791, 2014). "In contrast, both virgin wild-type mammary gland tissue and ErbB2TG tumour samples did not express any detectable HMGA2 protein, as would be expected." (PMID 23307470, 2013). "Neither Hmga1 nor Hmga2 were found to be expressed in virgin wild-type mammary tissue or ErbB2TG tumours analysed by qt-PCR." (PMID 23307470, 2013). "The level of HMGA2 expression among the five HCC cell lines coincided with their invasiveness, which was consistent with a previous observation that increased expression of HMGA2 correlated with increased invasiveness in tumor tissues." (PMID 23599793, 2013). "However, subcutaneous injection of HMGA2-depleted A673 and TC252 cells into NOD-SCID mice resulted in markedly reduced tumor growth, mimicking the effect of let-7a overexpression." (PMID 21853155, 2011). "A673 and TC252 cells expressing HMGA2 alone, let-7a alone or the combination of the two genes were injected subcutaneously into NOD/SCID mice, and the tumor forming ability of the different cell populations compared to that of their empty vector-infected counterparts." (PMID 21853155, 2011). "However, as observed in some C5 tumours, CH1 cells have amplification of HMGA2, suggesting this cell line has an alternative mechanism of HMGA2 over-expression." (PMID 21533284, 2011). "Inhibiting HMGA2 activity using suramin showed promising results in vitro with few non-specific effects, namely a significant anti-tumor effect by inhibiting cell invasion and reinducing differentiation, mimicking the effects resulting from knocking down HMGA2 by siRNA." (PMID 40004107, 2025). "However, the diagnostic role of HMGA2 IHC cannot be fully assessed yet as many tumor entities have so far not been examined for HMGA2 expression and data are controversial for most tumor entities that have been analyzed in multiple studies." (PMID 40518465, 2025). "Though potentially helpful in identifying HMGA2-altered lesions, the growth pattern itself is not necessarily indicative of unfavorable biological behavior, as the described neoplasms were benign and limited follow-up data to observe local recurrence was available." (PMID 40338436, 2025). "Notably, the upregulation of oncogenes, particularly Hmga2, alongside the tumour-suppressive function of miR let-7, highlights key molecular targets and potential therapeutic approaches for counteracting TPA-driven tumour development." (PMID 40182023, 2025).